HIF1A (hypoxia inducible factor 1 subunit alpha)
Diseases named in the same sentence as HIF1A in open-access papers (continued):
Sharing a sentence is not in itself a finding about the gene and the disease.
ischemia (continued). "Increasing HIF-1α expression can enhance tissue perfusion and vascular regeneration in ischemia situations such PAD, MI, stroke, and chronic wounds." (PMID 41150799, 2025). "The administration of Ginkgo biloba extract (EGb) significantly reduced infarct volume and inflammatory cytokine levels in ischemia/reperfusion mice via inhibiting the hypoxia-inducible factor-1α (HIF-1α)/HK2 signaling pathway." (PMID 40354372, 2025). "The AhR-/- control group had a significantly enhanced HIF-1α expression compared to the AhR+/+ control group as well as at the three-h post-ischemia group (*p = 0.0242)." (PMID 41452851, 2025). "(iii) Western blot analyses: Since the hearts of HIV-infected and HIV-1-infected mice treated with DTG/TDF/FTC showed reductions in the density of perfused microvessels (i.e., ischemia), Western blots were conducted for ischemia-induced protein, HIF-1α." (PMID 40332423, 2025). "Altogether, these data indicated that hMSC transplantation both augments angiogenesis and blunts fibrosis and inflammation after ischemia, while knockout of HIF-1α abrogates the angiogenic and therapeutic potential of hMSCs." (PMID 37158785, 2024). "Understanding more about disorders, including inflammation, cancer, and ischemia, is possible because of HIF-1α's effect on metabolic changes." (PMID 39099978, 2024). "Considering the importance of Hif1α during cardiac ischaemia, we screened for the top 100 genes that showed the highest correlation with Hif1α expression across the infarcted heart." (PMID 39308239, 2024). "On day 7, following ischemia, the mRNA levels of HIF-1α and PPARα returned to the levels observed in the control group." (PMID 38575595, 2024). "Activation of the CXCL12/CXCR4/ACKR3 axis is known to aid myocardial repair through ischemia-triggered hypoxia-inducible factor-1α (HIF-1α)." (PMID 38994928, 2024). "Hypoxia-inducible factor (HIF-1α) is a central transcription factor that detects cellular oxygen levels and rapidly responds pathophysiological ischemia." (PMID 37158785, 2024). "Ischemic-tolerant astrocytes express a purinoceptor called P2X7 receptor, which induces HIF1α and induces various neuroprotective molecules in a HIF1α-dependent manner, leading to ischemia tolerance." (PMID 38816814, 2024). "Consistently, suppression of HIF-1α upregulation characterizing a rat model of retinal ischemia exerts a protective action against ischemia itself and reduces retinal apoptosis." (PMID 38337691, 2024). "Inactivation of the HIF-1α subunit expression leads to increased brain damage and decreased survival after ischemia and to a more pronounced learning disorder and decreased neurogenesis in the post-ischemic period." (PMID 38069355, 2023). "During ischemia phase, both the excessive upregulation of hypoxia-inducible factor-1α (HIF-1α) and anaerobic metabolism play significant roles in direct cell injury posed by ischemia." (PMID 37021057, 2023). "The main findings were that the nuclear and cytoplasmic HIF1α immunoreactivity increased during reperfusion compared to pre-ischemia." (PMID 36908508, 2023). "During ischemia phase, curcumin can suppress the excessive upregulation of HIF-1α and anaerobic metabolism, reducing ischemia-induced injury on cells." (PMID 37021057, 2023). "During ischemia, TECs lead to pyruvate depletion and increased lactate levels in the renal cortex by inducing a shift in the HIF1α subunit from FAO to glycolysis." (PMID 37246731, 2023). "A recent study suggested that upon the insult of ischemia, exosomes including miR-19a-3p were secreted from cardiomyocytes that are absorbed by ECs, which inhibited their proliferation via HIF-1α downregulation." (PMID 37569674, 2023). "HIF-1α upregulation under hypoxic conditions orchestrates adaptive responses, potentially reducing cellular damage induced by ischemia, as seen in acute myocardial infarction." (PMID 37233182, 2023).
ischemia (continued). "Activation of HIF1A has been reported in animal models of intestinal ischemia-reperfusion, and has been shown to be critical for cell survival in myocardial and renal ischemia-reperfusion injury." (PMID 34774803, 2022). "It was found that the HIF-1α in the DRG was significantly enhanced 6 h following the hindlimb ischemia." (PMID 36589449, 2022). "β2 adrenergic receptor (β2-AR) antagonist alleviates ischemia-induced BBB injury by inhibiting HIF-1α expression and decreasing VEGF upregulation and the secretion of VEGF and MMP-2." (PMID 35656098, 2022). "Initial studies showed that mice with induced global Hif1a deletion (Hif1aloxP/loxP UbiquitinCre+) have exaggerated myocardial injury during in situ ischemia and reperfusion." (PMID 36247475, 2022). "During ischemia, oxygen and nutrient insufficiency induces HIF1A signaling, which helps the intestine to adapt to these stressful conditions by inducing metabolic alterations, angiogenesis, and barrier protection." (PMID 34774803, 2022). "In recent years, studies have shown that some chemicals that simulate hypoxia, such as cobalt chloride (CoCl2), iron chelators (deferoxamine), etc., can also induce cells to express HIF-1α and produce the corresponding ischemia under normoxic conditions." (PMID 35684364, 2022). "660-nm PBM induced a complex response in hASC spheroids, including HIF-1α upregulation, growth factor secretion, cytokeratin expression, angiogenesis, and vascularization in the ischemia model." (PMID 36104833, 2022). "VEGF expression is controlled by PGC-1α, as well as by HIF-1α, one of the crucial factors that determines the acquisition of the adaptive reaction in the brain to ischemia." (PMID 33806692, 2021). "Studies have shown that HIF1α knockout mice show better survival rates and improved neurological function in the early stage of ischemia." (PMID 33746762, 2021). "Histological analysis detected a massive increase in HIF1-α positive nuclei, documenting that during ischemia, HIF1-α translocates into the nucleus." (PMID 34573022, 2021). "Hif1α mRNA levels were decreased in the first and second-month post-ischemia, similar to those observed in the UNx group." (PMID 33888767, 2021). "Histological and ultrastructure analyses of corresponding brain tissue after ischemia confirmed such pivotal role of HIF-1α activation." (PMID 34205911, 2021). "In in vitro studies the upregulation of HIF-1α signaling was shown to improve cGMP production following ischemia through the maintenance of cGMP protein kinase activity, thus preventing the NO-mediated production of ROS/RNS instead of cGMP." (PMID 34439764, 2021). "We demonstrated that the overexpression of endothelial-cell ChT1 was dependent on HIF-1α during ischemia and gradually decreased with reperfusion." (PMID 34373737, 2021). "In this study, we demonstrate a novel regulatory mechanism in ischemic myocardium consisting of the direct interaction between LRP5 and PHD2, which influences the stability of HIF-1α, a key molecule involved in the protection of cardiac death under ischemia." (PMID 34205318, 2021). "By depleting cellular iron, DFO acts as a hypoxia-mimetic, bolstering the HIF-1α pathway and thus multiple aspects of the brain’s inherent neuroprotective defense against ischemia." (PMID 33513737, 2021). "They studied a rat model of intestinal ischemia/reperfusion (I: 1 hour/R: 2 hours), and their results show that the expression of HIF-1α increased in rats with I/R compared to controls." (PMID 33505452, 2021). "In the UNx group, Hif1a mRNA levels were significantly reduced in the first and second-month post-ischemia, whereas HIF1α protein levels remained unaltered during follow-up." (PMID 33888767, 2021). "Angiogenesis is mainly driven by ischemia and up-regulation of ischemia-induced transcription factors like HIF1a, and the genes that are responsive to these transcription factors, such as VEGFa and SDF1." (PMID 34630958, 2021).
ischemia (continued). "Impaired vasodilation and relatively lower GFR demonstrated ischemia of kidneys, which is in accordance with an increased renal HIF1α expression." (PMID 33928137, 2021). "During the early postpartum developmental stage, the rat retinal cells are affected by ischemia, which is correlated to the peak of expression of HIF-1α and VEGF-A, concomitantly with LC3." (PMID 33477313, 2021). "The HIF-1α dependent activation of eNOS transcription and subsequent NO release in the endothelium also contribute to reduction of ischemia infarct volume also shown in MCAO model." (PMID 34439764, 2021). "The positive effect in lieu of ischemia can be explained by the positive effect that the copper ions released from the cuprous oxide microparticles had on the expression of HIF-1α, and other angiogenic stimulating factors." (PMID 34684166, 2021). "A significantly high level of HIF-1α gene expression was registered in the ischemia group and rats treated with BM-MSCs compared with the control group." (PMID 34630958, 2021). "Upregulation of HIF-1α by exercise has been reported to play a role in reducing infarct volumes following ischemia/reperfusion injury, and in post-stroke neuroplasticity." (PMID 32670026, 2020). "Previous studies reported that HIF-1α upregulated VEGF expression and promoted angiogenesis, which suggests that it is vital in the rescue of tissue repair following ischemia-reperfusion-associated injuries." (PMID 32321591, 2020). "The expression level of HIF-1α in the Ischemia group was significantly higher than that in the Sham group." (PMID 32908557, 2020). "These authors found that with the withdrawal of glucose, less HIF-1α was stabilized than in an ischemia control group, despite ischemia." (PMID 32831635, 2020). "Recent studies suggest that the HIF-1α pathway appears to be suppressed early in response to severe ischemia." (PMID 32486245, 2020). "Two-way ANOVA revealed that the ligation of lumbar arteries significantly affected a change in the percentage of HIF-1α immunoreactive cells of ischemia discs compared to that of control discs." (PMID 31351455, 2019). "By modulating the stability of HIF1alpha messenger RNA, HIF1A has the capacity to regulate angiogenesis, an important component of the response of the heart to ischemia." (PMID 30678728, 2019). "The current study indicates that halofuginone is a possible drug for RGC degeneration induced by ischemia or high IOP inhibiting HIF-1α in the retina." (PMID 31261724, 2019). "HIF-1α immunoreactivity was clearly detected in the nuclei and cytoplasm in the AF and NP cells of both control and ischemia (cranial, bilateral and caudal) discs." (PMID 31351455, 2019). "HIF-1α signaling, which was involved in necroptosis, modulated blood–brain barrier integrity after focal ischemia." (PMID 31772561, 2019). "Immunohistochemical analysis showed that the ligation of lumbar arteries significantly affected a change in the percentage of HIF-1α immunoreactive cells of ischemia discs compared to that of control discs four weeks after the surgery (p < 0.05)." (PMID 31351455, 2019). "Our data indicated that astrocytic HO-1 induction increased HIF-1α levels in a mouse model of ischemia/reperfusion injury." (PMID 30153269, 2018). "Here, we demonstrate that this pharmacological approach, using the non-specific HIF hydroxylase inhibitor DMOG, was able to stabilize HIF-1α in IR cells, and improve recovery of cardiac function post-ischemia in diabetic rats." (PMID 30175272, 2018). "HIF-1α protein levels were 21% lower in diabetic hearts challenged with ischemia compared with control hearts." (PMID 30175272, 2018). "Inhibition of HIF-1α reduced blood-brain-barrier (BBB) damage after 2-h ischemia in a rat model of focal cerebral ischemia, and its downstream vascular endothelial growth factor (VEGF) and matrix metalloproteinase-2/9 (MMP-2/9)." (PMID 30647760, 2018).
ischemia (continued). "So, the observed nuclear location of HIF-1α in cardiomyocytes is clear evidence that the heart was affected by hypoxia-ischemia during the SE episode and remained injured by the persistent heart rate reduction." (PMID 29462915, 2018). "When both the 24-h and 5-day time points were considered collectively, the expression of HIF-1α protein in the cortex, outer medulla, and inner medulla was less after renal ischemia than after sham ischemia." (PMID 30110566, 2018). "Decreased HIF-1α protein accumulation was evident in both diabetic hearts challenged with ischemia, and in IR cardiomyocytes exposed to hypoxia." (PMID 30175272, 2018). "Molecular genetic studies have shown that the activity of hypoxia-inducible factor (HIF-1α) is closely related to ischemia-induced neuronal death." (PMID 30692904, 2018). "Treatment with dexmedetomidine at the beginning of reperfusion can inhibit autophagy of neurons by up-regulating HIF-1α, thereby protecting the brain from ischemia-reperfusion injury." (PMID 30692904, 2018). "A recent study showed that blocking β2-adrenergic receptor (β2-AR) alleviated ischemia-induced BBB injury by reducing hypoxia-inducible factor-1 alpha (HIF-1α) level." (PMID 30233326, 2018). "HIF-1α levels in the cortex were 88.3% less 5 days after renal ischemia than at the corresponding time-point after sham ischemia." (PMID 30110566, 2018). "A connection between HIF-1 and mTORC1 has been reported: Isoflurane preconditioning, which reduces neurological deficits, infarct volume, brain edema and apoptosis after ischemia induction, up-regulated HIF-1α expression via Akt/mTOR/p70S6K activation." (PMID 29497356, 2018). "The present study clearly demonstrated that the occlusion of the RVA induced ischemia, as evident by laser Doppler imaging and HIF1α expression." (PMID 30298003, 2018). "Consistent with TcPO2 monitoring results, lower expression level of Hif-1a was observed 48 hours after flap elevation at zone IV when arterial rather than venous supercharging was used, implying its higher anti-ischemia efficacy." (PMID 28187214, 2017). "We conclude that EPCs protected blood-brain barrier integrity after focal ischemia in diabetic mice through upregulation of HIF-1α signaling." (PMID 28697748, 2017). "All these findings demonstrate that miR-127-3p is a HIF-1α effector during the renal tissue repair after ischemia, among others." (PMID 28106131, 2017). "Previous data of our lab demonstrated that HIF-1α is stabilized in proximal tubule cells during ischemia and in late reperfusion." (PMID 28106131, 2017). "We also found that the combined treatment and the stabilization of HIF-1α were protective in both the in vitro primary neuron ischemia model and in the in vivo mouse stroke model in terms of maintaining cell viability and in the reduction of infarct size." (PMID 28566998, 2017). "We interpret the increased HIF-1α expression as a sign of the activation of this pathway following cocaine-induced vasoconstriction and ischemia, which triggered VEGF up-regulation and increased microvascular density, most markedly in cortical regions." (PMID 28448515, 2017). "The application of proteasome inhibitors in this study was mainly to investigate the mechanism of ROS mediated HIF-1α degradation in neurons during ischemia." (PMID 28566998, 2017). "During the hypoxic phase, HIF-1α expression in cross-clamped kidneys was detectable by 60 min, and its level continued to rise throughout the ischemia interval and post reperfusion." (PMID 27149666, 2016). "Previously, we reported that HHcy attenuation of PGC-1α and HIF-1α levels enhanced the likelihood of muscle atrophy and declined function after ischemia." (PMID 25608649, 2015). "During the early time of ischemia when administration of miR-335 mimic was found to be beneficial, HIF-1α protein levels were found to be low." (PMID 26030758, 2015).
ischemia (continued). "Some researchers have reported that HIF-1a is expressed in ileal mucosa cells after superior mesenteric artery occlusion or hemorrhagic shock (ischemia) in rats." (PMID 26098420, 2015). "On the contrary, during the late time of ischemia where administration of anti miR-335 was found to be beneficial, upregulation of HIF-1α protein was seen and it subsequently increased the expression level of its downstream genes." (PMID 26030758, 2015). "After ischemia–reperfusion, the number of HIF-1α positive neurons was significantly increased at each time point (p < 0.05)." (PMID 26715469, 2015). "It is well documented that activation of the HIF-1α protects the heart from ischemia or I/R induced injury." (PMID 25633836, 2015). "Cardiac-specific knockdown or knockout of PHD2, the major HIF-1α prolyl-4 hydroxylase in the heart, increases the myocardium capillary density and protects mice from myocardial injury induced by ischemia or I/R." (PMID 25633836, 2015). "In summary, post-ischemia treatment with Ast IV can attenuate myocardial IRI through activating HIF-1α/iNOS pathway, which transmits a survival signal to the myocardium." (PMID 25238237, 2014). "It has been shown that Per2 promotes circadian stabilization of HIF-1α activity that is critical for myocardial adaptation to ischemia." (PMID 25375852, 2014). "It has been reported that an increase in the level of HIF-1α is one of the first adaptive responses that occur at the molecular level of the myocardium to ischemia." (PMID 25238237, 2014). "In the cardiomyocyte model, two strategies were used to explore the role of HIF-1α in the protective effects of post-ischemia treatment with Ast IV." (PMID 25238237, 2014). "The effects of post-ischemia treatment with Ast IV on the expression of HIF-1α, iNOS, Bcl2, and Caspase3 were abolished by 2-MeOE2 (vs. SIR+Ast IV group, P<0.01)." (PMID 25238237, 2014). "The results confirmed that post-ischemia treatment with Ast IV can attenuate SIRI via HIF-1α activation, which transmits a survival signal to the myocardium." (PMID 25238237, 2014). "HIF-1α, a transcription factor, which is a major regulator of the hypoxic response of ischemia, plays a pivotal role in angiogenesis which can increase oxygen delivery." (PMID 24069057, 2013). "Iodothyronines seem also to stimulate angiogenesis through enhancing the expression of hypoxia inducible factor 1 alpha (HIF-1α), a transcription factor important for ischemia-induced coronary artery collateralization." (PMID 23555069, 2013). "Here, cerebral ischemia substantially increased HIF-1α activity 4 h post-ischemia, and this can be inhibited by the HIF-1α inhibitor 2-ME2 (100 mg/kg, i.p. daily for 20 days)." (PMID 23836498, 2013). "VEGF expression, enhanced by the hypoxia induced factor 1 alpha (HIF-1α) increases with ischemia and contributes to neuroprotection, neurogenesis and angiogenesis, as well as blood brain barrier protection." (PMID 21910904, 2011). "Ischemic conditioning seems to prevent HIF-1α mRNA induction in the rat liver after ischemia and reperfusion." (PMID 21771288, 2011). "Ischemia significantly increased the level of HIF-1α in the ipsilateral hemisphere, compared to the contralateral hemisphere." (PMID 22110762, 2011). "In this study, we investigated the neuroprotective effects of embryonic and postnatal NSPCs under conditions of ischemia, and the role of HIF-1α-regulated VEGF signaling in this process." (PMID 20339541, 2010). "Others have shown that upregulation of HIF-1α in neural progenitor cells enhances their ability to survive in vitro and following transplantation, as well as provide neuroprotection against ischemia." (PMID 20339541, 2010). "Elevated level of reactive oxygen species (ROS) and HIF-1α followed by deteriorated cell and tissue functions validated the chick embryo partial ischemia model." (PMID 20479865, 2010).